CD80 (CD80 molecule)
Diseases named in the same sentence as CD80 in open-access papers (continued):
Sharing a sentence is not in itself a finding about the gene and the disease.
tumor (continued). "PD-L1 also promotes tumor progression by reversing signaling through CD80 into T cells." (PMID 26279307, 2015). "Only when infiltrating tumor spheroids mPGES-1−/− macrophages expressed elevated CD80 levels." (PMID 25871398, 2015). "However, overall the tumor cell supernatants induced a more M2 prone phenotype with relatively high expression levels of IL-10 and low expression levels of M1 markers: IL-12, CD80 and HLA-DR." (PMID 25192022, 2014). "Tumor cell supernatants (CM) induced macrophages towards a M2 prone phenotype with relatively high expression levels of the M2 cytokine IL-10 and low mRNA levels of the M1 markers IL-12, CD80 and HLA-DR." (PMID 25192022, 2014). "This hypothesis was tested by inducing the expression of CD80/CD86 molecules on tumor cells prior to injection into mice." (PMID 23450201, 2013). "Early data suggested that introduction of the CD28 ligand B7-1 (CD80) into tumor cells could result in immune-mediated rejection in vivo." (PMID 24829752, 2013). "However, a few lines of evidence suggest that up-regulation of CD80 is the single most important factor that contribute to the T cell responses and tumor regression." (PMID 23671644, 2013). "Galiximab is a primatized anti-CD80 mAb that has been tested as monotherapy in phase I/II clinical trials involving patients with relapsed/refractory follicular lymphoma (FL), producing an overall response rate of 11% and tumor reductions in 46% of patients." (PMID 23764770, 2013). "Forced expression of CD80/CD86 in tumor cells resulted into CD8+ T cell-dependent tumor rejection." (PMID 23450201, 2013). "Thus, DAC-induced CD80 expression on tumor cells can directly enhance T cell activation and effector functions." (PMID 23671644, 2013). "Moreover, we did not observe any difference in the expression of 5 additional markers that are relevant for the interaction of lymphocyte and tumor cells (PD-1, CD80, CD86, PD-L1 and PD-L2)." (PMID 23284620, 2012). "Expression of CD80 was abundant on the tumor cells (82 ± 13%)." (PMID 23342263, 2012). "Additionally, low dose TBI did not increase the expression of the major histocompatibility complex (MHC) class II or the co-stimulatory molecule CD80 on tumor resident DCs or DCs located in the spleen or draining lymph nodes." (PMID 22911764, 2012). "The cell surface expression of CD80 was decreased in the tumour cells from the 5AC-treated animals, as compared with those from the untreated controls, while the B7-H1 molecules were moderately upregulated (a significant change was observed only in the CpG ODN/5AC-treated group)." (PMID 22015556, 2011). "Indeed, DCs detected in tumor tissue or local tumor draining lymph nodes (TDLN) of cancer patients display an immature phenotype defined by low expression of CD80, CD86 or CD83, and altered APC function." (PMID 20976125, 2010). "For example, there is evidence that HLA-G can be transferred from a tumour cell to a healthy cell, conferring the same NK cell suppression function that it had on the tumour cell and T-cells that acquired CD80 and HLA-DR from antigen presenting cells developed an antigen presenting-cell function." (PMID 20046883, 2009). "Moreover, immunization with a genetically modified tumor cell line, AGN2a-CD80/86, is even more effective when administered in the context of Treg blockade/depletion with an anti-CD25 mAb, PC61." (PMID 17397536, 2007). "To determine whether the local expression of CD70 and CD80 could affect tumor establishment, we sub-cutaneously injected 105 cells, from each type of tumor, into the flanks of C57BL/6 mice." (PMID 15279677, 2004). "We have previously shown that two co-stimulatory molecules (CD70 and CD80), expressed on the surface of tumor cells could induce an anti-tumor immune response when the cells were injected into a syngeneic animal." (PMID 15279677, 2004). "CD70 expression, alone or in association with a low level of CD80 expression, was not sufficient to induce anti-tumor immunity." (PMID 15279677, 2004).
tumor (continued). "In addition, targeting of CD86 and/or CD80 in experimental tumours, even of low immunogenicity, was found to promote antitumour CTL responses." (PMID 12771917, 2003). "For example, if there are active immune activation signals between some tumor subpopulations and T cells (such CD80/CD28 or IFNG/IFNGR), it could mean that the patient is more likely to respond to immunity therapy and could benefit from immune checkpoint inhibitors." (PMID 40842994, 2025). "PD-1/CD80 carried by I-sEVs promotes the secretion of PD-L1+ exosomes by tumor cells and reduces cell-surface PD-L1 expression, simultaneously inhibiting antigen-presenting molecules and intercellular adhesion molecules to ultimately induce an immunosuppressive “cold tumor” phenotype." (PMID 40881702, 2025). "Therefore, we investigated whether TAM polarization was altered in cinobufagin-treated tumors by initially assessing the expression of markers associated with the M1-like (CD80) tumor-suppressive phenotype and the M2-like (CD206) tumor-promoting phenotype." (PMID 39901195, 2025). "Thus, radiation-induced CD80 upregulation on myeloid cells in the tumor environment may be present in a range of inflammatory scenarios dependent on the adjuvant and inflammatory triggers that are present, and each may support Treg expansion." (PMID 41417245, 2025). "Thus, PD-1/CD80+ exosomes convert tumors to an immunologically cold phenotype through adaptive redistribution of PD-L1 in tumor cells, enabling tumor cells to shift PD-L1 expression to immune interaction sites, and thereby dampening cytotoxic T cell activation and promoting immune escape." (PMID 41294803, 2025). "Low expression of IL‐11 in tumour cells was associated with significantly higher levels of leukocytes (CD45), T cells (CD3, CD4, CD8), T‐cell activation (CD44, CD25, ICOS, Tim3), dendritic cell activation, antigen presentation (CD11c, CD80, B2M, HLA‐DR) and macrophage (CD68) markers." (PMID 40673604, 2025). "Hence, it may be postulated that treating patients with both anti-CTLA-4 and anti-CD80 antibodies may lead to a similar response rate in human tumours to that observed in mouse tumours." (PMID 40725864, 2025). "However, the tumor treated with combination therapy maintained CD80/CD86–CTLA-4 signaling." (PMID 39298276, 2024). "It was found that the stimulation of CD80 could Induce toxic effects of natural killer cells on CD80+K562 cells and suggested that these cells may be used for further development of therapeutic tumor vaccine." (PMID 39575257, 2024). "Finally, cells of different tumor types evade antitumor immunity via different expression of CD80." (PMID 39575257, 2024). "Therefore, I-sEV PD-1/CD80 could still interact with tumour PD-L1 and induce immunosuppression even in the presence of therapeutic antibodies." (PMID 38719909, 2024). "Therefore, the decline of CD80 positive cells in the present study may point to the activation of T-cell mediated anti-tumor immune response and a difference between the function of CD86 and CD80 in CCH seems likely." (PMID 38962703, 2024). "Upregulation of CD80 is speculated to promote a cytotoxic anti-tumor cell response." (PMID 39224452, 2024). "After tumor ablation, the remaining tumor debris was released from the tumor site to the 3D scaffolds stimulating the vaccine-like effect of R837 which promoted the recruitment and maturation of dendritic cells (DCs), as expressed by the percentage of mature DCs (CD11c+, CD80+, CD86+)." (PMID 38791452, 2024). "However, while tumour-retained CCR7+ DCs increase CD80/86 expression, concomitant downregulation of immunogenic transcriptional programmes obscures its functional significance, analogous to the increased expression of granzymes by terminally-exhausted CD8+ T cells." (PMID 38267413, 2024). "In addition, they also observed elevated expression of CD80 in higher tumor grades." (PMID 39575257, 2024).
tumor (continued). "Mechanistically, PD-1/CD80 carried on immunocyte-derived sEVs (I-sEV) increases secretion of PD-L1+ sEVs into circulation and decreases membrane expression of PD-L1, as well as antigen presentation and intercellular adhesion molecules, on tumour cells, leading to an immunologically ‘cold’ phenotype." (PMID 38719909, 2024). "Notably, residential macrophages, as identified through our single-cell analysis, were found to be upregulated in SCLC but were predominantly associated with the tumor-surrounding stroma, as evidenced by higher levels of CD163 and CD80 present in the immune stroma." (PMID 39231924, 2024). "However, interestingly, when we divided the patients into two groups according to the positivity of tumour cell surface PD-L1, the results showed that the levels of circulating PD-1/CD80+ sEVs positively correlated with those of PD-L1+ sEVs in patients with PD-L1-positive tumour cells." (PMID 38719909, 2024). "Moreover, PD-1/CD80+ sEVs might selectively interact with PD-L1+ tumour cells leading to more specific and efficient regulation of antitumour immunity." (PMID 38719909, 2024). "However, PD-1/CD80+ sEVs secreted by activated T cells could induce immunosuppression while reducing immunogenicity of tumour cells." (PMID 38719909, 2024). "Additionally, the expression of M1 macrophage markers CD86 and CD80 in tumor tissues surpassed that in adjacent tissues, while the expression of M2 macrophage markers CD163, CD206, and Arg-1 in tumor tissues was also higher than in adjacent tissues (p<0.05, p<0.01)." (PMID 39531417, 2024). "Therefore, with Förster resonance energy transfer (FRET), we first determined whether sEV PD-1/CD80 was transligated to tumour PD-L1 by evaluating their molecular proximity." (PMID 38719909, 2024). "In particular, CD80 with its later increase seems to be a useful indicator of CCH tumor cell maturation in this scenario, whereas the consistently high expression of CD86 may be interpreted as an indicator of an onset of tumor cell maturation earlier than the clinically apparent stage 1." (PMID 39619201, 2024). "Therefore, it was suggested that CD80 tend to be a potential target for tumor immunotherapy." (PMID 36892747, 2023). "However, tumor cells express positive costimulatory molecules, such as CD80 and CD86, at reduced levels that are insufficient to provide an effective second signal for T-cell activation, and thus, cannot effectively induce the anti-tumor immune response, generating immune tolerance instead." (PMID 37138865, 2023). "CD206+ M2 TAMs conventionally considered to be tumor-promoting have been shown to be capable of antigen cross-presentation, stimulation of antitumor immune responses, and tumor regression in mouse models of melanoma and colorectal cancer, due to concurrent CD80 expression." (PMID 37251409, 2023). "Conversely, CD80/CD86-targeted CAR-T (CTLA4-CAR), which comprises the extracellular and transmembrane portions of human CTLA4, the cytoplasmic region of human CD28, and the intracellular domains of human CD3z, was designed to destroy CD80/CD86-associated tumor cells in vitro and vivo." (PMID 37457699, 2023). "The expression of NUPR1 was highly correlated with tumor‐associated macrophage markers including C‐C motif chemokine ligand 2 (CCL2, R = 0.392, p < 0.001), C‐C chemokine receptor type 5 (CCR5, R = 0.323, p < 0.001), CD80 (R = 0.302, p < 0.001), and CD86 (R = 0.381, p < 0.001)." (PMID 36468653, 2023). "In addition, we also observed elevated expression of CD80 in higher tumor grades." (PMID 35814211, 2022). "In addition to TAMs correlation with tumor progression, there are some immunomodulatory proteins that have been reported in the last years to be overexpressed in various types of cancers, especially CD80 and mesothelin (MSLN)." (PMID 36387279, 2022).
tumor (continued). "Here the authors describe the design of the fusion therapeutic davoceticept (ALPN-202), based on a variant CD80 extracellular domain engineered to bind PD-L1 as well as CD28 and CTLA-4, providing direct T cell costimulation and dual checkpoint inhibition to enable anti-tumor immune responses." (PMID 35379805, 2022). "Meanwhile, the percentage of CD11c+, CD40+, CD80+, and CD86+ DCs significantly increased in the mCALR group, while no significant change was observed in the percentage of MHCII+ DCs, suggesting that mCALR expression was closely associated with DC infiltration in tumor tissues." (PMID 34660305, 2021). "Moreover, CD80 deactivation in tumor cells promoted tumor infiltration with APCs in our model." (PMID 33923750, 2021). "Others have shown that the paired expression of PD-1; PD-L1 on DCs is correlated with the tumor progression, loss of positive costimulatory markers (CD80, CD86, and CD40), a lack of cytokine release (IL-12, IL-10, IL-6, TNFα, and G-CSF), and contact-dependent inhibition of T cell expansion." (PMID 34078376, 2021). "Interestingly, it has been demonstrated that macrophage subpopulations differently distribute between the invasive front, internal tumor area or adjacent normal mucosa: CD68+ cells are located more in the tumor area, while CD80+ macrophages are highly expressed within the adjacent normal mucosa." (PMID 32650452, 2020). "The interaction of PD-L1 on tumor cells and CD80 on T cells suppresses T cell activation and survival, suggesting that dual blocking PD-1 and CD80 interaction with PD-L1 might be more favorable for improving the immunotherapy efficacy compared with single PD-1 blockade." (PMID 33178688, 2020). "In addition, compared to non‐tumor tissue infiltrating DCs, all tumor‐infiltrating DC subsets exhibited an increased CD80 expression together with an upregulation of CD40 for pDCs and cDC1s, while the level of CD86 was found to be downregulated on tumor‐infiltrating pDCs." (PMID 33282290, 2020). "Moreover, CD80 expression on naive, pre-activated T cells was induced upon co-culture with tumor-associated myeloid cells and levels of CD80 positive CD4 T cells after co-culture with tumor-associated myeloid cells was comparable to levels on CD4 TILs." (PMID 32071302, 2020). "Three macrophage markers were used to detect tumor-associated macrophages: CD68, which is a pan-macrophage marker, CD163, which is considered to stain for tumor-associated macrophages polarized toward an M2 phenotype, and CD80, which is more associated with M1-like macrophages." (PMID 30879106, 2019). "Thus, it may be tempting to speculate that reduced CD80 gene expression may confer an advantage to tumor growth." (PMID 30123257, 2018). "Notably, LPS injection decreased CD80 expression on CD11b+ cells in CT26 tumor-bearing mice." (PMID 29690614, 2018). "In addition, CTLA-4 expression on tumor specific Tregs could contribute to tumor immune escape by increasing the suppressive anti-tumor immunity and by downregulating CD80/CD86 on antigen presenting cells." (PMID 28073373, 2017). "However, cancer-associated microenvironment may adversely affect DC-related immune-surveillance system leading to defective DCs, which fail to upregulate important costimulatory surface molecule, CD80, and consequently ensue tumor escape and tolerogenicity." (PMID 28337449, 2017). "Therefore, it is possible that CT26/HER2 cells expressing CD80 may act as APCs, activating T cells and causing them to produce higher levels of IFN-γ, which likely block CTL induction during tumor progression." (PMID 28460461, 2017). "Therefore, CD80 does not appear to be associated with tumor progression through an increase in the production of IFN-γ in the CT26/HER2 tumor model." (PMID 28460461, 2017).
tumor (continued). "Thus, we evaluated whether intestinal epithelial cells isolated from healthy colonic mucosa (obtained far from active inflammation or neoplasm) could induce a CD80-dependent activation of syngeneic lymphocytes extracted from pericolonic lymph nodes." (PMID 25595911, 2015). "We investigated whether T cells expressing an anti-CD19, CD3 zeta and CD28-based CAR (19-28z) displayed the same proliferation and anti-tumor abilities than T cells expressing a CD3 zeta-based CAR (19z1) costimulated through the CD80/CD28, ligand/receptor pathway." (PMID 26110267, 2015). "Therefore, a possible mechanism for the APC-like behavior of tumor-activated γδ T cells is that these cells are loaded with tumor components for a brief period, during which they process and express costimulatory molecules CD80/CD86." (PMID 24741609, 2014). "Thus, DAC-induced CD80 expression triggers anti-tumor immunity in vivo." (PMID 23671644, 2013). "MHC class II expression on CD11c+ DCs increased at the tumor site, and MHC class I and CD80 expression increased on DCs in dLNs." (PMID 41541266, 2026). "Consistent with the tumor responses, EGFR‐19del LLC tumors contain significantly lower numbers of CD11c+MHC‐II+ DCs, which express reduced levels of CD80 and CD86, than the WT tumors." (PMID 41144813, 2026). "Remarkably, the EGFR mutant tumor cells products reduced the expression of HLA‐DR, CD86, and CD80 on DCs compared to WT cells (all p < 0.05), although they did not significantly alter the phagocytic ability of DCs." (PMID 41144813, 2026). "Within the tumor, rBCG promoted an increased frequency of MHC-II+ CD11c+ dendritic cells compared to both NT and BCG groups, accompanied by higher CD80 expression." (PMID 41522339, 2026). "We further quantified the spatial abundance of CD8a+ T cells, CD80+ M1 and CD206+ M2 macrophages in MTCQ1 tumors, which showed T cells located in the core of tumors and macrophages residing on tumor peripheries." (PMID 41141655, 2026). "At 48 hours post-treatment, an elevation in anti-tumor macrophage activation markers was observed, with increases in expression of MHCII, co-stimulatory markers CD86 and CD80, PDL1 and the migratory marker CCR7." (PMID 41048107, 2025). "In line with in vitro findings, tumor-infiltrating cDC1s exhibited elevated expression levels of CD40, CD80, and CD86 following DS treatment." (PMID 40625660, 2025). "The CD80− CD206+ M2 macrophage population was also similar in all tumors and groups, with the exception of the FMX group, where the M2 tumor macrophage levels were significantly higher when compared to the Ctrl group (p < 0.05)." (PMID 40400098, 2025). "Preclinical studies demonstrate that EZH2 inhibitors, tazemetostat and valemetostat, upregulate antigen HLA class I/II presentation machinery, OX40L, CD80 co-stimulatory ligands, and T cell-attracting chemokines, CXCL9 and CXCL10 in tumor cells." (PMID 41029427, 2025). "The expression of antigen-presenting biomarker (MHCII+, CD86+, CD80+) on macrophages and DCs was significantly enhanced in tumors treated with CAR-Ms, compared to the Con-Ms group tumor, indicating enhanced maturation and antigen-presenting function." (PMID 40814015, 2025). "To address alternative sources of CD80 and CD86 in the tumor environment, we profiled expression of these markers along with PDL1 (CD274) in published scRNASeq data from five different murine tumors including MC38." (PMID 41417245, 2025). "Direct interactions involve physical contact between immune and tumor cells, mediated by membrane-bound ligands and their respective receptors, including stimulatory and inhibitory signaling molecules like CD28, CD80, PD-1, and PD-L1." (PMID 40649953, 2025). "Recently an effect of CD80 and CD86 on tumor regression in canine cutaneous histiocytoma has been described." (PMID 40271486, 2025).